KRAS (KRas proto-oncogene, GTPase)
Diseases named in the same sentence as KRAS in open-access papers (continued):
Sharing a sentence is not in itself a finding about the gene and the disease.
lung cancer (continued). "Similar findings were observed for PFS in the small subset of patients with KRAS G12C-mutated lung cancer (N = 37) in KEYNOTE 189, but, in contrast to our study, no promising OS benefit was observed for the ICI combination." (PMID 36426286, 2022). "FAK may be surrogate markers of aberrant KRAS signaling found in aggressive phenotype in lung cancer." (PMID 35887120, 2022). "EGFR mutations are closely related to lung cancer in never smokers, whereas mutations in KRAS are strongly associated with lung cancer in people who are smoking." (PMID 36118777, 2022). "Likewise, pharmacological inhibition of BCL6 significantly impeded the growth of KRAS-mutant lung cancer cells both in vitro and in vivo." (PMID 36377663, 2022). "Thus, targeting NOP56 disrupts ROS homeostasis and induces IRE1α-mediated UPR in KRAS-mutant lung cancer cells." (PMID 35039048, 2022). "KRAS mutations have been observed to be related to poor prognosis in resected lung cancer, lack of survival benefit from adjuvant chemotherapy, and resistance to erlotinib or gefitinib." (PMID 35912232, 2022). "KRAS mutation subtypes such as G12D and comutations such as CDKN2/A and MET may modulate the immunotherapy responses and outcome in lung cancer." (PMID 36230855, 2022). "Mutant KRAS is a well-defined oncogenic driver in lung cancer." (PMID 36377663, 2022). "The MassARRAY-based OncoFOCUS panel (v3) was previously adopted in our community pathology lab as a fully validated clinical test of common mutations in BRAF, EGFR, KIT, KRAS, and NRAS genes, which are implicated in various cancers, particularly colon cancer, lung cancer and melanoma." (PMID 35446881, 2022). "Here we asked whether oncogenic signaling by KRAS and other oncogenes in lung cancer can perturb alternative splicing." (PMID 36522653, 2022). "To investigate the regulatory link between mutant KRAS and BCL6, we overexpressed different doxycycline-inducible G12 KRAS mutant variants (G12C, G12D, G12S, and G12V) in 293T cells, all of which commonly occur in human lung cancer." (PMID 36377663, 2022). "We analyzed the messenger RNA level of KRAS in different cancer types using the Oncomine database and found that KRAS is highly expressed in breast cancer, kidney cancer, lung cancer, myeloma, ovarian cancer, pancreatic cancer, and sarcoma compared to normal samples." (PMID 35563733, 2022). "In contrast, the anti-tumor effect of PBZ was not stronger than that of six other benzimidazoles tested, in the Z-score analysis for growth inhibition of KRAS-mutant and wild-type lung cancer cell lines, upon screening of 1271 compounds, where it was identified as one of 50 top-ranking compounds." (PMID 36230527, 2022). "Although EGFR, KRAS, and ALK mutations are generally considered mutually exclusive in NSCLC, recent studies have shown that above oncogenic driver mutations can co-exist in a certain amount of lung cancers." (PMID 36376839, 2022). "The study found that the KRAS gene-driven lung cancer ICI treatment response rate was the highest at 26%, followed by BRAF, with a response rate of 24%, and the MET-driven lung cancer ICI response rate was 16%, which were relatively higher than those of other driver genes." (PMID 35531878, 2022). "We have presented the incidence and characteristics of lung cancer patients harboring KRAS mutations in Taiwan, where more than half of the lung cancer patients were never-smokers." (PMID 35713442, 2022). "Consequently, co-targeting NOP56 and mTOR enhances apoptotic death of KRAS-mutant lung cancer cells in vitro and in vivo." (PMID 35039048, 2022). "One of the most sought‐after therapeutic targets in lung cancer is the KRAS oncogene." (PMID 34951114, 2022). "However, the development of targeted therapies for KRAS-mutant lung cancers has long been marked by failures." (PMID 36077640, 2022).
lung cancer (continued). "The majority of lung cancer incidents happen for KRAS mutants." (PMID 35409064, 2022). "Furthermore, shRNA targeting of KRAS prevented the TNF-ɑ hyperstimulation of NF-κB transcriptional activity in the A549 human lung cancer cell line, as measured by the abundance of its transcriptional targets COX2, ICAM1, and A20." (PMID 35359456, 2022). "This was further confirmed using the KRAS G12S mutant lung cancer cell line A549." (PMID 35364627, 2022). "The recent development ofKRASG12C inhibitors, which target the most common mutant form of theprotein in lung cancer, has shown that inhibiting KRAS-signalling in tumour cellspromotes anti-tumour immune responses and synergises with anti-PD-1 therapy in animmune-competent model of colorectal cancer." (PMID 35930804, 2022). "A small-molecule compound, oncarsin-1 was identified by synthetic lethality screening and was found to significantly suppress various lung cancers and might inhibit the novel KRAS/PKCι pathway." (PMID 35409064, 2022). "Recent advances in cancer biology and genomics research have allowed an in-depth characterization of lung cancers that have revealed new therapy targets (EGFR, ALK, ROS, and KRAS mutations) and have the potential of revealing even more biomarkers for diagnostic, prognostic, and targeted therapies." (PMID 35628157, 2022). "Our study highlights the promise and merits of targeting BCL6 to treat KRAS-mutant lung cancer." (PMID 36377663, 2022). "Moreover, AIMP2-DX2 levels are positively correlated with KRAS levels in colon and lung cancer cell lines and tissues." (PMID 35546148, 2022). "Molecular profiles of KRAS-mutant NSCLC were sequenced with 68 lung cancer-related gene NGS." (PMID 35887766, 2022). "In addition, univariate analysis with the Cox proportional hazard model shows that KRAS expression is significantly correlated with OS in lung cancer in different datasets, indicating the important potential of KRAS in these cancer types." (PMID 35563733, 2022). "As effective medicines have not yet been developed for mutant KRAS, this finding might provide a valuable option for treating lung cancer with mutant KRAS." (PMID 36230527, 2022). "Importantly, BCL6 depletion impeded lung tumorigenesis in a genetically engineered KrasG12D-driven mouse model, and pharmacological inhibition of BCL6 consistently reduced the growth of KRAS-mutant lung cancer cells and prolonged mouse survival." (PMID 36377663, 2022). "Therefore, BCL6 inhibition dramatically impaired the initiation of DNA synthesis, leading to elevated replicative stress and DNA damage, specifically in KRAS-mutant lung cancer cells in vitro and in vivo." (PMID 36377663, 2022). "KRAS mutations and EGFR mutations are the main mutations driving the development of lung cancer." (PMID 36176446, 2022). "Furthermore, the antitumor efficacy of XPO1 inhibitor selinexor against KRAS-mutant lung cancer patient-derived xenografts (PDX) was recently demonstrated." (PMID 35573474, 2022). "Additionally, we analysed the effect of dinaciclib on human cancer cell lines, including KRAS-mutated colon cancer (HCT116, SW480, and DLD1) and lung cancer (H460 and A549) cells." (PMID 35190631, 2022). "Gene expression ontology and immunocyte enrichment analysis showed that STK11 or KEAP1 mutation led to different immunophenotypes in KRAS mutation, but not in KRAS wild type and lung cancer." (PMID 36189266, 2022).
lung cancer (continued). "In a KRAS-driven murine lung cancer model, trametinib, a MEK inhibitor, directly depleted MDSCs." (PMID 36145516, 2022). "In addition, lung cancer cells treated with these hybrids loaded with siRNA targeting KRAS exhibited a four-fold higher KRAS knockdown as compared to cells treated with polyplexes." (PMID 35214000, 2022). "Similarly, Atg5 ablation in KRAS-driven mouse lung cancer models accelerated benign tumor formation, but restricted its progression to adenocarcinoma." (PMID 35727403, 2022). "KRAS is frequently mutated in pancreatic cancer, colorectal cancer (CRC), and lung cancer." (PMID 36531078, 2022). "In addition, overexpression of GATA3 was found in KRAS-driven lung cancer cells and further promoted the oncogenesis via microRNAs." (PMID 35936734, 2022). "We hypothesized that the others EGFR-positive KRAS mutant cancers were affected similar with EGFR-positive KRAS mutant lung cancers treated with R9VH36 and might reveal the different mechanism between the R9VH36 and EGFR-TKI." (PMID 35578244, 2022). "In lung cancers, non-small cell lung cancer showed a better prognosis in tumors with lower STING expression, and STING-expressing tumors showed a significantly higher frequency of EGFR and KRAS mutations." (PMID 35882970, 2022). "Interrogating the mutation signatures of human lung cancers similarly identified KRAS genomic driver mutations that failed to match the mutation signature of the tumor." (PMID 35482806, 2022). "Therapeutic targeting of the 26S proteasome could also be beneficial for solid tumors like TNBC patients, and in some cases for KRAS G12D lung cancer patients." (PMID 35088066, 2022). "In mouse models of KRAS mutant lung cancer, MEK inhibitors display strong anti-tumor activity." (PMID 36418460, 2022). "Previous studies reported that FRA1 promotes KRAS-induced lung cancer progression and metastasis." (PMID 34973117, 2022). "Further studies corroborate the importance of the IL-1/IL-17 axis also for KRAS-driven lung cancer." (PMID 36074553, 2022). "Instead, in the broader sample not restricted by PD-L1 expression included in the Lung Cancer Mutation Consortium study, 27% of 1655 patients had metastatic lung adenocarcinomas harboring a KRAS mutation." (PMID 35205788, 2022). "Previous studies have found that the abnormal activation of STAT3 in the development of KRAS mutant lung cancer, which will be attenuated under anti-IL-6 therapy, suggesting a tight association between IL-6/STAT3 signaling and inflammation in KRAS-activated tumorigenesis." (PMID 36619616, 2022). "Here, we identify B cell lymphoma 6 (BCL6) as a lynchpin in KRAS-driven lung cancer." (PMID 36377663, 2022). "However, due to the special structure of KRAS protein and the wide biological functions of the gene, the development of targeted therapy for KRAS mutant lung cancer has been frustrated for many years." (PMID 36376839, 2022). "The discovery of druggable targets such as epidermal growth factor receptor (EGFR), anaplastic lymphoma receptor tyrosine kinase (ALK), MET, ROS-1receptor tyrosine kinase and Kirsten rat sarcoma viral oncogene homolog (KRAS) open avenues for treating lung cancer." (PMID 35743687, 2022). "On the other hand, similar to ALK and ROS1 fusion-positive lung cancers, patients with NTRK fusion also can develop off-target resistance to TKI therapy, mechanisms including MET amplification, BRAF V600E mutation, or hotspot mutations involving KRAS." (PMID 36508072, 2022). "KRAS plays an important role in lung cancer and other types of cancer." (PMID 35634240, 2022). "However, mt KRAS lung cancer was found to be particularly resistant to such therapies, hence the need to develop a wider molecular profile and tailored therapies for this group of patients." (PMID 35877239, 2022).
lung cancer (continued). "Here we set outto develop mouse models of mutant KRAS-driven lung cancer with an elevated tumormutational burden by expressing the human DNA cytosine deaminase, APOBEC3B, tomimic the mutational signature seen in human lung cancer." (PMID 35930804, 2022). "The crosstalk of the MET and KRAS pathways could confer resistance to lung cancer-targeted therapies." (PMID 36230855, 2022). "Among the detected alternations, the eight-major driver mutations of lung cancer (EGFR, ALK, ERBB2, MET, RET, ROS1, BRAF, and KRAS) could be found in 14 out of 17 (82.4%) patients using both surgical and CNB specimens." (PMID 36224661, 2022). "Finally, we report that the cytoplasmic domain of iRhom2 is a hub for an ERBB-dependent positive feedback loop that maintains KRAS activity in lung cancer cells." (PMID 35971826, 2022). "Mutational activation of KRAS is a common oncogenic event in lung cancer, yet effective therapies are still lacking." (PMID 36377663, 2022). "Sotorasib is a KRAS G12C-targeting drug that was FDA approved in May of 2021 for the treatment of lung cancers that harbor mutant KRAS." (PMID 36011352, 2022). "As a result, different genetic alteration approaches were used in further investigations, and it was confirmed that the downregulation of PI3K suppresses KRAS-mutated lung carcinoma, but the effect was not so significant." (PMID 35409064, 2022). "KRAS is the most frequently mutated member of the RAS family, present in 96% of pancreatic ductal adenocarcinoma (PDAC), 52% of colorectal, 32% of lung carcinomas, and to a lesser extent in a variety of other cancers, with alterations mostly occurring at codon G12, G13, and Q61." (PMID 35053550, 2022). "RALA and RALB can have redundant roles, such as in KRAS-driven lung carcinoma." (PMID 35626682, 2022). "Anti-PD1 and anti-PDL1 are now approved to treat lung cancer when targeted therapy is not available, such as in patients with KRAS mutations that are not KRAS-G12C mutations, for which sotorasib is now approved." (PMID 34638488, 2021). "Two types of KRAS mutant lung cancer cells, in specific A549 and H460, were used." (PMID 34781949, 2021). "Moreover, many studies have described the genetic susceptibility to develop lung cancer especially in North Africa by identifying genetic biomarkers in EGFR, KRAS and ALK genes." (PMID 33937056, 2021). "Serine threonine phosphatase PP2A inhibition could confer MEK inhibitor resistance in KRAS-mutant lung cancer cells." (PMID 34301278, 2021). "However, the combination of ARS-1620 and FGFR selective inhibitor infigratinib displayed the greatest antiproliferative effect in a panel of KRAS G12C-mutant cells, including several lung cancer cell lines." (PMID 34068816, 2021). "In addition, combined inhibition of MEK and SHP2 showed high efficiency in engineered or xenograft KRAS-mutant pancreas, ovarian, and lung cancer, overcoming the rapid resistance to MEK inhibitor as a single therapy." (PMID 34301278, 2021). "Interestingly, resistance to MEK inhibitors is caused by the feedback activation of FGFR1-FRS2 pathway in mesenchymal-like KRAS-mutant lung cancer cell lines, NCI-H1792 and LU99." (PMID 34068816, 2021). "In our study, a decrease of SDPR was found in lung cancers as well as in KRAS-mutant subgroup, and which may be a promising prognostic marker for the survival of patients with lung cancer." (PMID 33435990, 2021). "Importantly, EGFR signaling activation has been recently shown to be an important escape mechanism upon KRAS inhibition or gemcitabine treatment in lung cancer and PDAC cancer, respectively." (PMID 33670598, 2021). "Ongoing clinical trials assessing the efficacy of KRAS inhibitors in lung cancer." (PMID 34722241, 2021).
lung cancer (continued). "XPO1 has been proposed as a therapeutic target in several tumors including KRAS-mutant lung cancer." (PMID 33777798, 2021). "Conversely, RAS activation causes resistance to FGFR1 inhibitors in FGFR1-amplified lung cancers, suggesting that both FGFR1 and KRAS alterations can sustain aberrant MAPK pathway activation and drive reciprocal resistance to targeted drugs in lung cancer therapy." (PMID 34858498, 2021). "First, the observation that lung cancer cells with mutant or wild-type KRAS are sensitive to the three-drug treatment suggests this approach may have clinical utility against at least some tumors with mutant KRAS, an important need." (PMID 34862367, 2021). "Furthermore, KRAS has been reported to promote lipogenesis through the induction of fatty acid synthase in lung cancer." (PMID 33777798, 2021). "Furthermore, anti-mutant KRAS siRNA-loaded hybrid nanoparticles (AKSLHNs) have been shown to target the KRAS and inhibit the metastasis in a mouse model of lung cancer." (PMID 33740988, 2021). "The molecular testing of lung cancer usually screens for genes encoding epidermal growth factor receptor (EGFR), anaplastic lymphoma kinase (ALK) and Kirsten rat sarcoma viral oncogene homolog (KRAS)." (PMID 33747933, 2021). "Additionally, we observed high BLT2 expression in tissue samples from patients with KrasG12D-expressing lung adenocarcinoma, supporting the contributory role of BLT2 in KRAS-driven human lung cancer." (PMID 34635780, 2021). "This study elucidated regulation network of SDPR in KRAS-mutant NSCLC, and it illustrated correlations between low SDPR expression and suppressed immune system, unfolding a prognostic factor and potential target for the treatment of lung cancer, especially for KRAS-mutant NSCLC." (PMID 33435990, 2021). "In patients, KRAS mutations combined with copy number gains were associated with decreased survival in lung cancer compared to KRAS mutations without copy number gains (LOH due to uniparental disomy or no LOH)." (PMID 33924994, 2021). "Additionally, for cancer, several clinical trials are ongoing, e.g., targeting G12D-mutated KRAS mRNA in advanced pancreatic cancer, targeting STAT3 mRNA in metastatic NSCLC, or HSP27 mRNA in lung cancer, metastatic bladder cancer, or prostate cancer." (PMID 34439281, 2021). "Indeed, we observed that the KrasG12D mutant stimulated p38 kinase activity in the lung tissues of a KRAS-driven lung cancer mouse model." (PMID 34635780, 2021). "Here, we aim to describe the tumor heterogeneity of KRAS mutant lung cancers and its immune-regulatory role, to report the efficacy with current immunotherapies, and to overview the therapeutic approaches targeting KRAS mutant tumors, other than KRAS G12C inhibitors." (PMID 35096591, 2021). "KRAS mutant tumors lacking the WT allele (KRASm/WT−) were more prevalent in lung cancer cell lines compared to other tumor types." (PMID 34573384, 2021). "Although lung cancer is the leading cause of cancer-related deaths worldwide and KRAS is the most frequently mutated oncogene in lung cancer cases, the mechanism by which KRAS mutation drives lung cancer has not been fully elucidated." (PMID 34635780, 2021). "Similarly, therapies that counteract the oncogenic effects of mutant KRAS are still in development, as lung cancers driven by mutant KRAS remain among the most refractory to available treatments." (PMID 33889302, 2021).